ENSG00000212626
Synonyms: LOC124900409
Gene: Small nucleolar RNA gene on chromosome 18 (7,301,020 to 7,301,153, reverse strand). Ensembl gene ENSG00000212626.
Gene Ontology:
Biological process: RNA processing
Cellular component: nucleolus
Homologues: Paralogues in human: SNORA48 (87% identical), SNORA48B (84% identical).